ZNF232 (zinc finger protein 232)
Description:
May be involved in transcriptional regulation.
Synonyms: ZSCAN11
Tractability: PROTAC: ubiquitination databases record sites on it.
Gene: Protein-coding gene on chromosome 17 (5,105,269 to 5,123,162, reverse strand). Ensembl gene ENSG00000167840.
Subcellular location: Nucleus
Subcellular location (Human Protein Atlas): Nucleoplasm; Cytosol; Vesicles
Gene Ontology:
Molecular function: protein binding; DNA-binding transcription factor activity, RNA polymerase II-specific; RNA polymerase II cis-regulatory region sequence-specific DNA binding
Biological process: regulation of transcription by RNA polymerase II
Cellular component: nucleoplasm; nucleus
Genetic constraint (gnomAD): Loss-of-function variants: 26 observed, 26.88 expected, observed/expected ratio (o/e) 0.97, 90% interval 0.71 to 1.34. The upper end of that interval is the gene's LOEUF score, 1.34, which puts it in group 5 of 6, group 1 being the genes least tolerant of losing a copy. Missense variants: 519 observed, 550.78 expected, observed/expected ratio (o/e) 0.94, 90% interval 0.88 to 1.01. Synonymous variants: 193 observed, 194.04 expected, observed/expected ratio (o/e) 0.99, 90% interval 0.88 to 1.12.
Homologues: Orthologues: chimpanzee ZNF232 (99% identical), guinea pig ZNF232 (71% identical), pig ZNF232 (70% identical), rabbit ZNF232 (61% identical). Paralogues in human: ZNF397 (44% identical), ZSCAN31 (43% identical), ZSCAN30 (43% identical), ZKSCAN1 (43% identical), ZKSCAN3 (42% identical), ZKSCAN4 (42% identical), ZKSCAN8 (42% identical), ZNF165 (40% identical), ZSCAN21 (40% identical), ZSCAN12 (39% identical), ZSCAN26 (39% identical), ZSCAN23 (39% identical), and 18 more.
Diseases named in the same sentence as ZNF232 in open-access papers:
ZNF232 is named in the same sentence as 3 diseases in open-access papers, as found by Europe PMC text mining. Sharing a sentence is not in itself a finding about the gene and the disease. The quoted sentences say what the papers report.
Alzheimer disease (1 paper, 2019). A progressive, neurodegenerative disease characterized by loss of function and death of nerve cells in several areas of the brain leading to loss of cognitive function such as memory and language. "The ZNF232 locus was associated with a family history of Alzheimer’s disease in a GWA meta-analysis." (PMID 31744183, 2019).
ZNF232 also shares sentences with these, for which no sentence is quoted: autoimmune disease (1 paper); oligodendroglioma (1).